RN7SL737P (RNA, 7SL, cytoplasmic 737, pseudogene)
Gene: Miscellaneous RNA gene on chromosome 12 (93,509,487 to 93,509,768, forward strand). Ensembl gene ENSG00000243015.
Homologues: Orthologues: chimpanzee Metazoa_SRP (96% identical). Paralogues in human: RN7SL1 (83% identical), RN7SL3 (82% identical), RN7SL2 (82% identical), RN7SL230P (82% identical), RN7SL126P (80% identical), RN7SL45P (80% identical), RN7SL664P (80% identical), RN7SL91P (80% identical), RN7SL709P (80% identical), RN7SL769P (80% identical), RN7SL326P (80% identical), RN7SL177P (79% identical), and 702 more.